CCR3 (C-C motif chemokine receptor 3)
Description:
G protein-coupled receptor (GPCR) that plays a key role in the immune system by regulating the migration and activation of white blood cells in response to chemokines. Selectively interacts with eosinophil-attracting chemokines such as eotaxin/CCL11, eotaxin-2/CCL24 and eotaxin-3/CCL26. Ligand binding triggers intracellular signaling that leads to chemotaxis of immune cells. Mechanistically, signals through GNA14 or GNA16 to induce stimulation of phospholipase Cbeta/PLCB2 and subsequently chemotaxis. Alternatively, transduces signal via GNAI1 resulting in elevated intracellular calcium levels and activation of the PI3K/AKT pathway. May also act as a possible functional receptor for NARS1. (Microbial infection) Alternative coreceptor with CD4 for HIV-1 infection.
Synonyms: C C CKR3; CC-CKR-3; CKR 3; CKR3; CD193; CMKBR3
Tractability: Small molecule: a high-quality ligand is known; it belongs to a druggable protein family. Antibody: its Gene Ontology location is reachable by antibodies, with high confidence; UniProt places it where antibodies can reach, with medium confidence; UniProt predicts a signal peptide or a membrane-spanning region; the Human Protein Atlas places it where antibodies can reach. PROTAC: a small molecule that binds it is known.
Target class: Chemokine receptor; Peptide receptor (family A GPCR); Family A G protein-coupled receptor; CC chemokine receptor; Membrane receptor
Chemical probes: CHEMBL250689, PD081601, PD083344
Gene: Protein-coding gene on chromosome 3 (46,130,890 to 46,266,706, forward strand). Ensembl gene ENSG00000183625.
Subcellular location: Cell membrane
Subcellular location (Human Protein Atlas): Plasma membrane
Pathways (Reactome):
Signal Transduction: Chemokine receptors bind chemokines; G alpha (i) signalling events
Gene Ontology:
Molecular function: C-C chemokine binding; C-C chemokine receptor activity; protein binding; chemokine receptor activity; G protein-coupled receptor activity
Biological process: cell chemotaxis; chemokine-mediated signaling pathway; phospholipase C-activating G protein-coupled receptor signaling pathway; positive regulation of angiogenesis; adenylate cyclase-modulating G protein-coupled receptor signaling pathway; calcium-mediated signaling; cell adhesion; cellular defense response; chemotaxis; immune response; inflammatory response; positive regulation of cytosolic calcium ion concentration; cellular response to cytokine stimulus; G protein-coupled receptor signaling pathway; positive regulation of endothelial cell proliferation
Cellular component: plasma membrane; cytoplasm; external side of plasma membrane; membrane
Genetic constraint (gnomAD): Loss-of-function variants: 1 observed, 0.55 expected, observed/expected ratio (o/e) 1.83, 90% interval 0.34 to 1.92. That is too few expected variants to judge how well the gene tolerates losing a copy. Missense variants: 415 observed, 457.73 expected, observed/expected ratio (o/e) 0.91, 90% interval 0.84 to 0.98. Synonymous variants: 202 observed, 187.88 expected, observed/expected ratio (o/e) 1.08, 90% interval 0.96 to 1.21.
Homologues: Orthologues: chimpanzee CCR3 (99% identical), macaque CCR3 (92% identical), dog CCR3 (69% identical), mouse Ccr3 (69% identical), pig CCR3 (68% identical), rat Ccr3 (67% identical), guinea pig CCR3 (66% identical), tropical clawed frog ccr2 (48% identical), zebrafish cabz01093075.1 (39% identical), zebrafish ccr8.1 (39% identical), zebrafish si:ch211-207g17.3 (38% identical), zebrafish ccr2 (36% identical), and 2 more. Paralogues in human: CCR1 (63% identical), CCR2 (50% identical), CCR5 (49% identical), CCR4 (44% identical), CCRL2 (38% identical), CX3CR1 (37% identical), CCR8 (36% identical), ACKR2 (34% identical), CCR6 (32% identical), CCR9 (32% identical), CCR7 (32% identical), CXCR3 (30% identical), and 11 more.
Diseases named in the same sentence as CCR3 in open-access papers:
CCR3 is named in the same sentence as 192 diseases in open-access papers, as found by Europe PMC text mining. Sharing a sentence is not in itself a finding about the gene and the disease. The quoted sentences say what the papers report.
asthma (76 papers, 2008 to 2025). "CCR3 is implicated in numerous allergic diseases including asthma, eosinophilic esophagitis, and atopic dermatitis making the CCR3 axis another attractive pharmaceutical target." (PMID 40975172, 2025). "Most of ligands to CCR3 are associated with asthma, and CCR3 has become an appealing possibility in asthma treatment or therapy." (PMID 23737822, 2013). "Most of the ligands to CCR3 are associated with asthma, and CCR3 has become an appealing possibility in asthma treatment or therapy." (PMID 23737822, 2013). "In summary, PT, CR and their combinational prescription have deep inhibitory effects on airway inflammation in a murine model of asthma and it was caused by suppression of Th2 cytokines (IL-4, IL-5, IL-13), IgE, eosinophil CCR3 expression in lung." (PMID 19657453, 2009). "Furthermore, the CCL11/CCR3 axis has been implicated in facilitating breast cancer lung metastasis under conditions of asthma-associated chronic inflammation, suggesting a potential link between allergic inflammation and cancer progression." (PMID 40429807, 2025). "Currently, there are no clinically approved CCR3 antagonists: antagonist tolerance may have been the cause of failure of the previously tested CCR3 antagonist in clinical trials against asthma." (PMID 37575219, 2023). "With CCR3 having an association with many of the cells and chemokines involved in asthma and allergy, it is theorized that blockade of this receptor may have marked effects in eosinophilic diseases." (PMID 33917396, 2021). "The reports that upregulated expression of CCR3 on eosinophils are associated with asthma and that the number of activated basophils is increased in the sputum of patients with eosinophilic asthma may support the notion that CCR3+ granulocytes are involved in AA and ARA." (PMID 40534099, 2025). "Clinical studies have demonstrated a strong correlation between elevated CCR3 and ligand expression levels with disease severity in asthma patients, underscoring its therapeutic potential for eosinophil-mediated inflammatory disorders." (PMID 40429807, 2025). "For example, the controversial CCR3+ basophils in allergic individuals, and increased CD203c+ basophils were observed in the blood from patients with asthma exacerbation." (PMID 40534099, 2025). "High CCL28 levels are present in airway biopsies from asthma patients, and CCR3+ and CCR10+ cells are recruited to the airways in a CCL28-dependent fashion in murine asthma models." (PMID 39193987, 2024). "The expression levels of ITGA4 and ITGB2 in IL‐5‐activated eosinophils and that of CCR3 in IL‐5‐ or IL‐17‐activated eosinophils were significantly higher for patients with asthma than for normal individuals." (PMID 39575691, 2024). "CCR3 receptor activation in atherosclerosis increases endothelial permeability in the coronary arteries and pharmaceutical companies have targeted CCR3 to block the Th2 immune response for treatment of severe asthma." (PMID 38332938, 2024). "In a guinea pig asthma model, eosinophils migrate into nerves, particularly the vagal nerve, via a CCR3-dependent pathway and release MBP, which acts as a muscarinic receptor 2 antagonist." (PMID 39518415, 2024). "CCR3 seems to be a target for asthma and allergy, but ongoing studies present a potential role of CCR3 antagonism in two disorders associated with the aging population, such as macular degeneration (MAD) and cognitive dysfunction in mice models." (PMID 37834457, 2023). "These broader categories, involving questions regarding the role of CCR3 in the pathogenesis of asthma, potentially overshadow the molecular mechanisms at play, such as tolerance." (PMID 37575219, 2023). "The activation of CCR3 by eotaxins (eosinophil chemotactic proteins) induces inflammation and thus is involved in asthma and allergies, including allergic skin diseases." (PMID 37834457, 2023).
asthma (continued). "The signaling pathways mediated by chemokines and the CC chemokine receptor 3 (CCR3) are important for the discovery of asthma medications." (PMID 35455087, 2022). "CCR3 is one of the most relevant chemokine receptors in asthma, and its ligands are CCL3, CCL5, CCL11, and CCL13." (PMID 35743888, 2022). "A number of other chemokines from the eotaxin family of proteins, including RANTES; MIP-1; and MCP-2, 3, and 4; many of which are elevated in asthma and correlate with disease severity, also bind to CCR3." (PMID 33917396, 2021). "Li and others reported that hsa-miR-30a-3p regulates eosinophil activity through targeting CCR3 in asthma." (PMID 34336929, 2021). "This study suggested that miR-30a-3p was involved in asthma by regulating eosinophil activity and targeting CCR3." (PMID 33313407, 2020). "Several studies revealed that CCR3 downregulation inhibited eosinophil recruitment in an acute model of asthma." (PMID 33313407, 2020). "More importantly, 11 mRNAs were overlapped in our sequencing data, MalaCards database and asthma-associated genes, including IL4, IL-10, MMP9, VCAM-1, Il1rl1, Alox5, Il1rn, Ccr3, Cysltr1, Epx, and Ccl24." (PMID 31231429, 2019). "CCR2 receptor blockade prevented asthma in a primate model, and anti-CCR3 and anti-CCR4 were tested in asthma." (PMID 29670611, 2018). "Several chemokines, especially eotaxin, help to attract eosinophilia into the airway via CC chemokine receptor 3 (CCR3) in asthma." (PMID 28106744, 2017). "C-C chemokine receptor type 3 (CCR3) is involved in the development of allergic diseases such as allergic rhinitis, asthma and atopic dermatitis." (PMID 28046055, 2017). "It is also noteworthy the presence of two eosinophil-related pathways shared solely by asthma and eczema: CCR3 signaling in Eosinophils and The role of eosinophils in the chemokine network of allergy." (PMID 28598986, 2017). "BMS-639623 and GSK766994, two potent CCR3 antagonists, are also in clinical trials for treating asthma." (PMID 27119233, 2016). "CCL13 is a potent chemokine which attracts CCR3+ cells like eosinophils, Th2-lymphocytes, basophils and correlates with asthma exacerbation." (PMID 24612750, 2014). "In asthma, CCR3 and 7 are expressed by airway smooth muscle (ASM) and CCR7 has been implicated in the development of ASM hyperplasia." (PMID 19735481, 2009). "Our findings provide evidence that PT, CR and their combinational prescription play a regulatory role in allergic inflammation and offer therapeutic approaches as novel CCR3 antagonists for treatment asthma." (PMID 19657453, 2009). "For this reason, the plans for clinical development of many CCR3 antagonists in asthma have been put on hold." (PMID 18315837, 2008). "Some small molecules targeting CCR3 were developed for asthma; they could be repurposed for IBD if eosinophil-driven pathology is confirmed." (PMID 40860650, 2025). "Stimulation with exosomes from asthmatic eosinophils also enhances CCR3 and VEGFA gene expression: CCR3 activation initiates proliferation through the MAPK cascade, while VEGFA is associated with bronchial wall remodeling, a characteristic of asthma." (PMID 40722500, 2025). "Consistent with the association between high DNAm scores and T2-high asthma, we observed overexpression of canonical T2 genes implicated in the pathways or directly targeted by current biologic therapeutics, including IL1RL1, CCR3, and IL5RA10,53,54." (PMID 40950420, 2025). "CCR3 plays a key role in triggering cell proliferation via the MAPK pathway, and its activation likely leads to the abnormal proliferation of ASM cells, a hallmark of airway remodeling in asthma." (PMID 39518415, 2024). "Inhibiting CCR3 has demonstrated efficacy in reducing Th2 immune responses for treatment of severe asthma, and our group found the Th2 immune response itself to be positively associated with increased infarct volume and edema in stroke patients undergoing thrombectomy." (PMID 38332938, 2024).
asthma (continued). "Although the eotaxin–CCR3 pathway is required for eosinophil trafficking, the CCR3 receptor is also present on other cells known to have effector functions in asthma, including basophils, mast cells, CD34 + cells, airway epithelial cells, and activated T cells." (PMID 33917396, 2021). "Therefore, our results suggest new strategies for the treatment of advanced PCa, involving CCR3 antagonists, which are currently being developed for other diseases including asthma." (PMID 33671469, 2021). "Indeed, there have been early phase clinical trials with CCR3 antagonists for asthma and, more recently, a therapeutic antibody against eotaxin-1/CCL11 (Bertilimumab) for allergic rhinitis." (PMID 29962972, 2018). "CCR3 has been widely studied in both clinical and experimental models of asthma." (PMID 27795621, 2016). "Another mouse model of asthma revealed that a CCR3 monoclonal antibody could significantly suppress airway eosinophilia and mucus production without decreasing IL-5 levels in BALF." (PMID 27275740, 2016). "Pinelliae rhizome and Citrus reticulata and their combinational prescription have deep inhibitory effects on airway inflammation in a murine model of asthma and it was mediated by suppression of Th2 cytokines (IL-4, IL-5, IL-13), IgE, eosinophil CCR3 expression in lung." (PMID 24367979, 2013). "Our data indicate that CF has profound inhibitory effects on airway inflammation in a mouse model of asthma, and these effects were caused by the suppression of Th2 cytokines (IL-5), B cell-dependent production of OVA-specific IgE, and eosinophil CCR3 expression." (PMID 22439901, 2012). "Analysis was done of the relationship between the genotypes defined by the combination of CCR5Δ32, CCR2-G190A, and CCR3-T51C polymorphisms in relation to asthma with or without atopy." (PMID 20220260, 2010). "In addition, eotaxin-3 could be a key regulator during the recruitment of eosinophils in asthma via activating CCR3 specifically." (PMID 37200921, 2023). "However, the differences in phenotypes between sputum eosinophils in the examined groups might indicate the future direction of personalized therapy in COPD and asthma, e.g., with CCR3 monoclonal antibody." (PMID 37371101, 2023). "Therefore, we hypothesized that miR-30a-3p may play an important role in asthma progression by regulating the expression of CCR3." (PMID 33313407, 2020). "In conclusion, the findings suggested that miR-30a-3p mimic significantly reduced eosinophil viability and migration and induced apoptosis via targeting CCR3, indicating that miR-30a-3p might participate in the development and progression of asthma through regulating eosinophil activity." (PMID 33313407, 2020). "Therefore, it was hypothesized that miR-30a-3p may be involved in the development and progression of asthma via targeting the CCR3 signaling pathway and regulating eosinophil activity." (PMID 33313407, 2020). "Accordingly, CCR3 may be a treatment target in allergic rhinitis and asthma." (PMID 20144207, 2010). "Here we demonstrated that SR1001 prevents CCL11/CCR3-induced ERK phosphorylation in eosinophils, possibly by increasing BMAL1 and thereby impeding this crucial pathomechanism of asthma." (PMID 40131242, 2025). "Corresponding proteins from many of these DEGs have already been identified as drug targets for the treatment of various diseases such as COVID-19, asthma or rheumatoid arthritis (e.g., CCR2, CCR3, CXCL8, JAK3, HRH, CA4, see clinicaltrials.gov)." (PMID 38242945, 2024). "The credibility of results has been verified by selecting four genes (IL5RA, CCR3, IL13RA2, TNFRSF8) which were upregulated in Asthma groups, but downregulated in ART + Asthma groups, according to the log2 (fold change) value." (PMID 36998616, 2023). "Monocytes and eosinophils in sputum from children with asthma exhibited CCL13 and CCR3, but lymphocytes solely expressed CCL13; CCL13 is negatively correlated with peak expiratory flow and is downregulated in asthma remission." (PMID 37153575, 2023).
asthma (continued). "Intriguingly, in our study, ZKPC was found to be able to resist the supernatant of M2-induced decrease in cell viability and apoptosis, and reduce the levels of chemokine receptors, CCR3, and CCR4, which are involved in lung inflammation in asthma." (PMID 34608825, 2021). "Chemokine receptor-3 (CCR3) ligands (CCL11, CCL24, and CCL26) accelerate epithelial wound closure in vitro, with epithelial CCR3 expression upregulated in human asthma." (PMID 33562816, 2021). "CP and OA were shown to significantly inhibit airway and lung inflammation, mucus secretion, lymphocytes, neutrophil and eosinophil infiltration, AHR, and inflammatory mediators such as IL-5, IL-13, CCR3, MUC5AC, and COX-2 in the mouse model of asthma." (PMID 33806085, 2021). "Platelets also express certain types of chemokine receptors (CCR3, CCR4, CXCR4) of pertinence to pulmonary cellular recruitment during asthma, although the physiological significance of these observations has not yet been fully elucidated." (PMID 33556295, 2021). "By interacting with CCR3, CCL24 (C-C motif chemokine ligand 24, also known as eotaxin-2) is an important mediator in Th2 cell-mediated allergic inflammation occurring in asthma, allergic rhinitis, and atopic dermatitis." (PMID 32826979, 2020). "We here report high-level production in E.coli of 4 human GPCRs, namely chemokine receptors (hCRs) CCR5, CCR3, CXCR4 and CX3CR1 that are directly involved in HIV-1 infection, asthma and cancer metastasis." (PMID 19223978, 2009). "The expression levels of IL17RA, IL4RA, integrin β2, CCR3, FCER1A, TGFB1, TLR‐3, TLR‐7, and TLR‐9 in eosinophils treated with IL‐17 for 3 h were higher for normal individuals than for patients with asthma." (PMID 39575691, 2024). "The relevant role of CCR3 in asthma pathology is also supported by the evidence that the airways of patients with asthma contain more cells expressing mRNA for CCR3 and its ligands than non-asthmatic controls." (PMID 36140282, 2022). "A recent study, with R321 (a CCR3 antagonist that self-assembles into nanoparticles and binds CCR3 directly), showed that treatment inhibits eosinophil lung homing and AHR in a murine model of asthma." (PMID 33669458, 2021). "The mechanisms of asthma and eczema were found to be identical for three pathways: Regulation of hematopoiesis by cytokines, GATA3 participate in activating the Th2 cytokine genes expression, and CCR3 signaling in eosinophils." (PMID 28598986, 2017). "Also, chemokine receptors like CCR3, CCR4, and CCR8 have been found to be elevated in asthma patients and experimental murine models." (PMID 27795621, 2016). "However, recombinant and ASM-derived CCL11 was inactivated by β-tryptase and co-culture with mast cells and as mast cells are located within the ASM bundle in asthma this questions the importance of ASM CCR3 activation in disease." (PMID 19735481, 2009). "However, some trials, like those involving CCR1/AZD4818 for COPD, CCR3/GSK766994 for asthma, and CCL2/Carlumab for IPF, have shown no efficacy." (PMID 39768150, 2024). "Therefore, the selective blockade of the CCR3-eotaxin-1/CCL11 axis could impair eosinophil recruitment, representing an attractive target for the treatment of asthma, allergic rhinitis, and other eosinophil-related conditions." (PMID 29962972, 2018). "However, in another animal model of asthma, a CCR3 antagonist did not decrease the number of eosinophils in lung tissues but only antigen-induced clustering of eosinophils along the airway nerves." (PMID 18315837, 2008). "For other asthma-relevant genes such as TNF, IL-4, IL-10, CCL12 (MCP-5), CCL5 (RANTES), and CCR3, there were no significant IL-13-inducible or statin effects on gene expression." (PMID 22583375, 2012).